BRCA1 (BRCA1 DNA repair associated)
Diseases named in the same sentence as BRCA1 in open-access papers (continued):
Sharing a sentence is not in itself a finding about the gene and the disease.
breast cancer (continued). "It was shown that reconstitution of exogenous BRCA1 in the BRCA1-mutant HCC1937 breast cancer cell line resulted in enhanced sensitivity to PTX." (PMID 26900348, 2016). "Our main goal was to evaluate haplotyping of three intragenic markers of BRCA1 between breast cancer patients and healthy women." (PMID 27351029, 2016). "It is known that breast cancer associated with BRCA mutations are more likely to be associated with young age and in the case of BRCA1 mutations with triple negative phenotype." (PMID 27149669, 2016). "Mutations in the breast and ovarian cancer susceptibility genes, BRCA1 and BRCA2, are responsible for the majority of hereditary cases of breast cancer and ovarian cancer." (PMID 27229687, 2016). "In the present study we identified miRNAs related to breast cancer subtypes and demonstrated that miR-498, a triple negative-specific miRNA, regulates BRCA1 expression." (PMID 26933805, 2016). "We found that the spectrum of BRCA1 and BRCA2 germline mutations in Chinese high risk breast cancer patients are much smaller than those in Caucasian patients, and little has been recognized in this field." (PMID 26852015, 2016). "BRCA1 and BRCA2 mutations account for approximately 16% of the familial risk of breast cancer and are also associated with increased risk of pancreatic, stomach, laryngeal, fallopian tube and prostate cancer." (PMID 27037238, 2016). "For instance, 5.8% of positive results among women with breast cancer were in highly penetrant genes other than BRCA1/2." (PMID 26681312, 2016). "For example, only 13 of the 1,791 BRCA1 variants and three of the 2,000 BRCA2 variants in the Breast Cancer Information Core (BIC) database were derived exclusively from mainland Chinese patients." (PMID 26848529, 2016). "Nevertheless, most of the TNBC patients are presenting with sporadic breast cancer and only 9–15 % of all patients within the TNBC subgroup were reported to possess a BRCA1 mutation." (PMID 27756336, 2016). "The association between the presence of mutations in BRCA1 and BRCA2 genes and an increased risk of developing breast cancer is well known." (PMID 27149669, 2016). "A significant percentage (45 %), of the tumors included in this study was from patients with a family history of breast cancer (the Swedish average is 35 %) with BRCA1 and BRCA12 accounting for 8 % and 3 %, respectively." (PMID 27357824, 2016). "BRCA1 and BRCA2 (with 70 and 59 variants, respectively) accounted for 39.1% of positive findings, meaning the majority of positive results identified in women with breast cancer were in genes other than BRCA1/2." (PMID 26681312, 2016). "For women with a significant family history of breast cancer, genetic testing of BRCA1/2 is available as a routine clinical test for the diagnosis of HBOC in the US and other western countries." (PMID 26981296, 2016). "BRCA1 mutations are responsible for up to 10% of the epithelial ovarian cancers (EOC) and 15% of breast cancers." (PMID 28164176, 2016). "This concept has been practically applied for the treatment of breast cancer patients that are defective in BRCA1/2 with PARP inhibitors." (PMID 27167194, 2016). "More importantly, all p16;Brca1 compound mutant mammary tumors are poorly differentiated basal-like tumors with enriched TICs and activated EMT features." (PMID 27811360, 2016). "Methylated BRCA1 in breast cancer specimens correlated with increased mitotic index, the negativity of Her2 receptors, and hence molecular subtype “luminal A” (p = 0.042, p = 0.007, and p = 0.049, resp)." (PMID 27413552, 2016).
breast cancer (continued). "Given variable genetic and epigenetic alterations among these breast cancer cell lines, we predicted that some cell lines had lost the BRCA1/NEAT1/miR-129- 5p regulation axis." (PMID 27556296, 2016). "We therefore investigated the recruitment of BRCA1 and Pol-I occupancy at rDNA one hour after UV (100 J/m2) or X-ray (6 Gy) treatments in different breast cancer cells." (PMID 27589844, 2016). "The results suggest that the tumour suppressive role of BRCA1 is partially achieved by regulating FOXO3 expression in breast cancer." (PMID 27043660, 2016). "Depletion of Brca1 leads to defects in mouse mammary gland development and mammary tumors in humans and mice." (PMID 27043663, 2016). "To evaluate the transcriptional activity of PR receptors in BRCA1 mutated tissues, we examined the expression level of fatty acid synthase (FASN), a PR-induced target gene that is associated with tumor growth of breast cancer cells." (PMID 27246982, 2016). "PB reduces DNA- dependent protein kinase (DNA-PK) expression and inhibits NHEJ (Non Homologous End Joining) activity in BRCA1 defective breast cancer cells." (PMID 27220670, 2016). "The breast cancer susceptibility genes, BRCA1 and BRCA2, are responsible for a high proportion of cases of hereditable breast cancer." (PMID 27377827, 2016). "We have confirmed that ALDH1 positivity is the best marker for the identification of BCSCs in BRCA1-defective breast cancer cell lines when compared to the CD marker profile and Side Population (SP) analysis." (PMID 27229859, 2016). "Clinically actionable mutations in BRCA1, BRCA2 and ERBB2(HER2) were detected in 5.5% of patients, while 53% had genomic alterations matching ongoing or concluded breast cancer studies." (PMID 27901097, 2016). "The probability of an individual to carry a BRCA1 or BRCA2 germline mutation is based primarily on clinical data such as family history, age at diagnosis of breast cancer and ethnicity." (PMID 27129401, 2016). "We investigated the promoter methylation status of BRCA1 and HORMAD1 to explore if aberrant methylation of these candidate drivers of genomic instability in basal-like breast cancer was associated with subsets of ET7 tumors." (PMID 26923702, 2016). "These also included the 1,250 non-BRCA1/2 breast cancer patients and 800 controls from the RBCS study that were used in the whole gene screen to evaluate the quality of the genotyping assay." (PMID 27424772, 2016). "In BRCA1/BRCA2 mutation carriers, PBSO/RRSO not only decreases the risk of development of ovarian cancer by 80-90 % and breast cancer by 40–50 %, but also reduces mortality due to cancer of the genital tract and overall mortality." (PMID 26928677, 2016). "This is because the ALDH1+ cells from BRCA1-defective cell lines formed large mammospheres in comparison to ALDH1+ cells from BRCA1-competent breast cancer cells." (PMID 27229859, 2016). "Taken together, our data provide a comprehensive description of drug vulnerabilities of existing BRCA1-mutant breast cancer cell lines." (PMID 27313062, 2016). "Expression of BRCA1 and BRCA2 in CMT was analyzed and it was found to be associated with an increased mammary tumor risk in English Springer Spaniels (ESS)." (PMID 27657059, 2016). "In breast cancer, for example, the BRCA-1 and BRCA-2 genes indicate a strong dependency between BRCA-gene types and lymphatic and hematogeneous metastatic spread." (PMID 27601051, 2016). "Since this is the same Cre transgene used to induce mammary tumors in our conditional Brca1-null mouse model, the consequences of Ctip and Brca1 inactivation can be compared in a common biological setting." (PMID 27058754, 2016). "It has been found that BRCA1-defficient breast cancer cell lines have increased XIST expression suggesting it to be used as a marker to study tumour development." (PMID 30159409, 2016).
breast cancer (continued). "Here we aimed to identify studies evaluating mutations in BRCA1 or BRCA2 genes and clinical outcome in breast cancer to assess the influence of age and hormonal receptor expression on survival." (PMID 27149669, 2016). "Expression of the CA9 protein and the BRCA1 (breast cancer 1) protein are inversely correlated in patients with breast cancer." (PMID 27478411, 2016). "We have shown that BRCA1 co-immunoprecipitates with active Pol-I transcription factors from nuclear extracts of untreated breast cancer cells." (PMID 27589844, 2016). "We next tested if the interactions between BRCA1 and Pol-I machinery were affected by DNA damage by performing BRCA1 imunoprecipitation from nuclear extracts prepared from breast cancer cells one hour after UV (100 J/m2) or X-ray (6 Gy) treatments." (PMID 27589844, 2016). "Of these, 1826 patients had sporadic breast cancer, 33 had BRCA-positive cancer (19 BRCA1-mutated and 14 BRCA2-mutated) and 66 had BRCA-wild type breast cancer." (PMID 27899083, 2016). "Direct evidence shows that progression from BRCA1-methylated normal breast epithelial cells to BRCA1-methylated breast cancer needs to be investigated in future studies." (PMID 27413552, 2016). "This pilot study aimed to investigate the contribution of BRCA1 and BRCA2 mutation to early onset and familial cases of breast cancer in Uzbekistan." (PMID 29138730, 2016). "Taken together, 4,520 familial non-BRCA1/2 breast cancer cases and 3,127 controls were genotyped including the cases and controls of the whole gene screen." (PMID 27424772, 2016). "BRCA1 methylation is observed in approximately 11–14% of breast cancers and 5%–31% of ovarian cancers." (PMID 26967246, 2016). "Our experiments showed no major impact on growth characteristics of human ovarian (OVCAR5) and breast cancer (Cal51) cell lines upon BRCA1 knockdown." (PMID 27845331, 2016). "DNA methylation in the BRCA1 promoter region is one of the most important epigenetic silencing mechanisms, which relates to breast cancer tumorigenesis and development." (PMID 27027444, 2016). "BRCA1 promoter methylation has also been suggested as a predictor for overall and disease free survival in breast cancer patients." (PMID 27027444, 2016). "BRCA1-mutant breast cancers respond well to platinum agent therapy, which induces DNA crosslinking, as the tumors are deficient in DNA repair; however, cisplatin resistance often develops." (PMID 27806319, 2016). "This is the maiden study addressing the ability of PB to target CSCs with selectivity for BCSCs from BRCA1-defective breast cancer cell lines." (PMID 27229859, 2016). "BRCA1 and BRCA2 are two tumor suppressor genes which have been proven to be breast cancer susceptibility genes." (PMID 27428375, 2016). "Pathogenic variants were identified in 11.8% (6/51) of male patients with breast cancer and were found in BRCA1, BRCA2, CHEK2, and PALB2; one man was positive for both a BRCA1 and CHEK2 variant." (PMID 26681312, 2016). "In agreement, our result also show that BRCA1 suppresses proliferation of basal type breast cancer cell line HCC70, at least partially through FOXO3, as depletion of FOXO3 by siRNA compromised the cell proliferation suppression induced by BRCA1 overexpression." (PMID 27043660, 2016). "There was a significant difference between BRCA1-related and sporadic breast carcinomas in terms of CDH3-positive cases (p < 0.001)." (PMID 27566577, 2016). "We showed that expression of TOP1 and CDH3 was significantly increased in human BRCA1-related breast carcinomas relative to sporadic cases (p = 0.002 and p < 0.001, respectively)." (PMID 27566577, 2016). "About 74% of BRCA1-related breast carcinomas, 23% of BRCA2-related breast carcinomas and 13% of sporadic breast carcinomas had triple negative phenotype lacking ER, PgR and HER2 expression (p < 0.001)." (PMID 27566577, 2016).
breast cancer (continued). "In line with the findings of this study, the expression of BRCA1/2 predicted shorter survival of breast carcinoma and ovarian carcinoma." (PMID 27643881, 2016). "When TOP1 and CDH3 were combined, there was a significant association between breast carcinomas with positive TOP1 and CDH3 and BRCA1/2 mutations (adjusted OR 5.05; 95% CI, 1.75–14.6, p = 0.003)." (PMID 27566577, 2016). "BRCA1 promoter methylation is an essential epigenetic transcriptional silencing mechanism, related to breast cancer (BC) occurrence and progression." (PMID 27027444, 2016). "More importantly, we validated two candidate proteins demonstrating, in accordance with animal data, increased expression in human BRCA1-related breast carcinomas." (PMID 27566577, 2016). "Comparison between BRCA1-related and sporadic breast carcinomas demonstrated a significant difference in TOP1 expression (p = 0.002)." (PMID 27566577, 2016). "Multiple logistic regression was performed to estimate the predictive effects of TOP1 or CDH3 for BRCA1/2-related breast carcinomas when adjusted for triple negative breast cancer and age." (PMID 27566577, 2016). "According to the Breast Cancer Information Core (BIC), more than 1800 and 2000 distinct variants of the BRCA1 and BRCA2 genes have been described, respectively." (PMID 25948282, 2015). "Treatment with lycopene increases BRCA1 gene expression in breast cancer cell line MCF-7 and HBL-100." (PMID 25636033, 2015). "When the cancer sera were tested against a combination of two antigens, higher frequency (P < 0.01) of autoantibodies against PARP1 and BRCA1 was found in breast cancer and ovarian cancer." (PMID 25865228, 2015). "First and second primary breast tumors have been shown to share some risk factors, including mutations in BRCA1 and BRCA2, family history of breast cancer, and obesity." (PMID 26751177, 2015). "Two double heterozygous breast cancer cases were identified in the TNBC group (one patient was BRCA1/CHEK2 and the other was BRCA1/NBN)." (PMID 26083025, 2015). "The use of PARP inhibitors are likely to be beneficial in specific tumors, such as in BRCA1-positive breast cancer cells." (PMID 26733491, 2015). "Ever since BRCA1 hypermethylation was proved to be involved in sporadic breast cancer, some studies were dedicated to explore the correlation between its aberrant methylation and the disease characteristics." (PMID 25789047, 2015). "BRCA1 plays a role in regulation DNA repair activity and BRCA1mutation contributed to development of breast cancer, ovarian cancer, pancreatic cancer, and gastric cancer." (PMID 25646628, 2015). "This study aims to compare grade independent miRNA expression in luminal cancers, sporadic and BRCA1 basal-type breast cancers." (PMID 26152113, 2015). "Previously, it has been shown that BRCA1 gene expression is relatively low in ER-negative and high-grade breast cancers and that BRCA1 gene expression is significantly down-regulated in triple-negative breast cancers." (PMID 26392359, 2015). "Note that here, used a reference sample because there are three groups of interest: BRCA1 mutation, BRCA2 mutation, and sporadic cases of breast cancer." (PMID 25910040, 2015). "The aim of the present study was to investigate BRCA1 gene expression, methylation status and clinical significance in sporadic types of breast cancer." (PMID 25789047, 2015). "Using ovarian and breast cancer cellular models with known BRCA1 status, we evaluated their HR functionality by RAD51 foci formation assay." (PMID 26510816, 2015).
breast cancer (continued). "Our inability to find a relation between BRCA1 expression and basal-like breast cancers supports the concept that the phenotypic similarities of sporadic basal-like breast tumors and hereditary BRCA1 mutated tumors may be explained by factors other than BRCA1 dysfunction." (PMID 25825707, 2015). "In AhR-activated human breast cancer cells, the pattern of BRCA-1 promoter CpG methylation coincided with the one detected in human sporadic breast tumors." (PMID 26715507, 2015). "Conversely, αNF antagonized E2-dependent stimulation of BRCA-1 expression in ERα-positive MCF-7 breast cancer cells." (PMID 26715507, 2015). "The estimated carrier frequency for women diagnosed with breast cancer under 50 years of age, at 0.5%, is lower than that estimated for BRCA1/BRCA2 carriers in the same population." (PMID 25925845, 2015). "Clinical-pathological information and follow-up data were collected from nine breast cancer studies from the Breast Cancer Association Consortium (BCAC) (n = 5,752) and from one study of familial breast cancer patients with BRCA1/2 mutations (n = 107)." (PMID 26137966, 2015). "PARP inhibitors are now applied in the clinic for BRCA1/2 defective ovarian and breast cancers and are in clinical trial for a variety of other BRCA1/2-defective tumors." (PMID 25988138, 2015). "We report here that EPA significantly up-regulates the expression of BRCA1 in human breast cancer cells." (PMID 25762631, 2015). "To further elucidate the cross-talk between expression and/or activation of AhR, and BRCA-1 regulation, we turned to cell culture experiments using UACC-3199 sporadic breast cancer cells, which possess hypermethylated BRCA-1 promoter and express low ERα." (PMID 26715507, 2015). "We demonstrate further that a diet rich in EPA strongly induces expression of BRCA1 in human breast cancer xenografts." (PMID 25762631, 2015). "Our data further suggests that IGF-1R inhibition suppresses HR by downregulation of RAD51, and that this allows a strong antitumor activity in combination with PARP inhibitors in BRCA1 wild-type (HR proficient) ovarian and breast cancer cells." (PMID 26510816, 2015). "Other studies support these data, in which familial BRCA1 breast cancers have shared features with a subset of sporadic tumours, indicating a similar aetiology." (PMID 26387133, 2015). "A significant positive correlation between PIG3 and BRCA1 expression was identified using the breast cancer tissue-array (r = 0.678, P < 0.001)." (PMID 25797244, 2015). "We found that Pit-1 down-regulated DNA-damage and repair genes, and specifically inhibited BRCA1 gene expression, sensitizing breast cancer cells to DNA-damage agents." (PMID 25992773, 2015). "The discovery of the BRCA1 and BRCA2 genes as major breast cancer susceptibility genes led to great advances in the genetic screening for the disease and the understanding of its inheritance." (PMID 25923920, 2015). "It is expected that rapid genetic counseling and testing (RGCT) will lead to increasing numbers of breast cancer (BC) patients knowing their BRCA1/2 carrier status before primary surgery." (PMID 25700605, 2015). "In particular, our experimental validation showed the positive correlation for BRCA1-miR-143-miR-145 pairs in breast cancer subtypes." (PMID 25961039, 2015). "Other genomic variations (for example, in genes encoding proteins interacting with BRCA1 and BRCA2) have been identified as modifiers of breast cancer risk and increase or decrease the risk initially conferred by BRCA1 or BRCA2 mutation." (PMID 25925750, 2015). "According to the literature, 5 (12%) of 41 breast cancer cell lines have BRCA mutations and 28 (68%) of the 41 cell lines have BRCA1 allelic loss." (PMID 25975349, 2015).